TRBV20OR9-2 (T cell receptor beta variable 20/OR9-2 (non-functional))
Synonyms: TRBV20/OR9-2; TCRBV20S2; TCRBV2S2O; CDR3; TCRBV2O
Gene: T-cell receptor variable (V) gene on chromosome 9 (33,617,845 to 33,618,508, forward strand). Ensembl gene ENSG00000205274.
Gene Ontology:
Biological process: cell surface receptor signaling pathway
Cellular component: plasma membrane
Homologues: Orthologues: mouse Trbv20 (55% identical). Paralogues in human: TRBV20-1 (89% identical), TRBV29-1 (62% identical), TRBV12-5 (28% identical), TRBV6-1 (28% identical), TRBV6-5 (28% identical), TRBV4-2 (27% identical), TRBV6-2 (27% identical), TRBV6-4 (27% identical), TRBV19 (26% identical), TRBV3-1 (26% identical), TRBV6-7 (26% identical), TRBV6-8 (26% identical), and 39 more.
Diseases named in the same sentence as TRBV20OR9-2 in open-access papers:
TRBV20OR9-2 is named in the same sentence as 8 diseases in open-access papers, as found by Europe PMC text mining. Sharing a sentence is not in itself a finding about the gene and the disease.
TRBV20OR9-2 shares sentences with these, for which no sentence is quoted: tumor (4 papers); autoimmune disease (2); infection (2); cancer (1); coeliac disease (1); influenza (1); liver fibrosis (1); T-cell lymphomas (1).